RYBP (RING1 and YY1 binding protein)
Description:
Component of a Polycomb group (PcG) multiprotein PRC1-like complex, a complex class required to maintain the transcriptionally repressive state of many genes, including Hox genes, throughout development. PcG PRC1-like complex acts via chromatin remodeling and modification of histones; it mediates monoubiquitination of histone H2A 'Lys-119', rendering chromatin heritably changed in its expressibility. Component of a PRC1-like complex that mediates monoubiquitination of histone H2A 'Lys-119' on the X chromosome and is required for normal silencing of one copy of the X chromosome in XX females. May stimulate ubiquitination of histone H2A 'Lys-119' by recruiting the complex to target sites (By similarity). May also regulate the ubiquitin-mediated proteasomal degradation of other proteins like FANK1 to regulate apoptosis. May be implicated in the regulation of the transcription as a repressor of the transcriptional activity of E4TF1. May bind to DNA (By similarity). May play a role in the repression of tumor growth and metastasis in breast cancer by down-regulating SRRM3.
Synonyms: APAP-1; DEDAF; YEAF1; AAP1
Tractability: PROTAC: UniProt records ubiquitination sites on it; ubiquitination databases record sites on it; its protein half-life has been measured.
Gene: Protein-coding gene on chromosome 3 (72,371,825 to 72,446,621, reverse strand). Ensembl gene ENSG00000163602.
Subcellular location: Nucleus; Cytoplasm; Nucleus, nucleoplasm
Subcellular location (Human Protein Atlas): Nucleoplasm
Pathways (Reactome):
Gene expression (Transcription): RUNX1 interacts with co-factors whose precise effect on RUNX1 targets is not known; Transcriptional Regulation by E2F6
Gene Ontology:
Molecular function: nucleic acid binding; protein binding; DNA binding; transcription coregulator activity; transcription corepressor activity
Biological process: chromatin remodeling; negative regulation of proteasomal ubiquitin-dependent protein catabolic process; positive regulation of apoptotic process; positive regulation of DNA-templated transcription; heterochromatin formation; negative regulation of DNA-templated transcription; regulation of DNA-templated transcription
Cellular component: cytoplasm; nucleoplasm; nucleus; PcG protein complex; chromatin; PRC1 complex
Genetic constraint (gnomAD): Loss-of-function variants: 0 observed, 17.39 expected, observed/expected ratio (o/e) 0, 90% interval 0 to 0.17. The upper end of that interval is the gene's LOEUF score, 0.17, which puts it in group 1 of 6, group 1 being the genes least tolerant of losing a copy. Missense variants: 131 observed, 224.96 expected, observed/expected ratio (o/e) 0.58, 90% interval 0.5 to 0.67. Synonymous variants: 89 observed, 84.15 expected, observed/expected ratio (o/e) 1.06, 90% interval 0.89 to 1.26.
Homologues: Orthologues: chimpanzee RYBP (99% identical), dog RYBP (99% identical), macaque RYBP (99% identical), pig RYBP (99% identical), guinea pig RYBP (99% identical), rabbit RYBP (99% identical), mouse Rybp (99% identical), rat Rybp (99% identical), tropical clawed frog rybp (83% identical), zebrafish rybpb (80% identical), zebrafish rybpa (70% identical), Drosophila melanogaster RYBP (34% identical), and 1 more. Paralogues in human: YAF2 (53% identical).
Diseases named in the same sentence as RYBP in open-access papers:
RYBP is named in the same sentence as 43 diseases in open-access papers, as found by Europe PMC text mining. Sharing a sentence is not in itself a finding about the gene and the disease. The quoted sentences say what the papers report.
hepatocellular carcinoma (7 papers, 2014 to 2024). A malignant tumor that arises from hepatocytes. "Alterations in RYBP expression have been associated with various biological processes and diseases, including tumor cell invasion, Hodgkin disease, and liver carcinoma." (PMID 39604829, 2024). "In accordance with our findings, overexpression of RYBP has been linked with a better prognosis in hepatocellular carcinoma and non-small cell lung cancer (NSCLC)." (PMID 34845670, 2022). "Additionally, RYBP mutations have been implicated in changes in body height, progression of liver carcinoma, and neoplasm metastasis." (PMID 39604829, 2024). "In fact, several studies have shown that the expression of RYBP is dysregulated in various human tumor tissues, including prostate, lung, liver, breast, hepatocellular carcinoma, glioblastoma, Hodgkin lymphoma, and cervical cancer." (PMID 38785968, 2024). "Another study indicated that RING1 and YY1 binding protein (RYBP) overexpression remarkably inhibits the proliferation, migration, and invasion of hepatocellular carcinoma cells." (PMID 34845670, 2022). "In this study, RYBP overexpression inhibited hepatoma cell invasion, and decreased the expression of E-cadherin and increased the expression of vimentin in vitro and in vivo." (PMID 25344099, 2014). "In most of the hepatoma cell lines, both the mRNA and protein levels of RYBP were lower than those in the normal hepatocytes." (PMID 25344099, 2014). "Interestingly, RYBP has been also shown to inhibit cancer cell migration and invasion in breast, lung and hepatocellular carcinomas." (PMID 36233063, 2022). "In other types of cancer, such as hepatocellular carcinoma, ETS1 has been found to act as a tumor suppressor and inhibit tumor cell proliferation by targeting RYBP." (PMID 38649363, 2024). "We also examined the RYBP expression in immortalized human normal hepatocytes (CL48) and hepatoma-derived cell lines." (PMID 25344099, 2014).
breast carcinoma (5 papers, 2014 to 2025). "In breast cancer, RYBP overexpression has been associated with tumor suppression by inhibiting cell proliferation and metastasis via the regulation of proteins such as cyclin A, cyclin B1, and E-cadherin." (PMID 40867231, 2025). "Overexpression of RYBP in breast cancer cells and lung cancer cell also significantly impaired cell proliferation, migration, and invasion ability." (PMID 34845670, 2022). "RYBP plays a tumor suppressor gene role in breast cancer by inhibiting breast cancer cell proliferation and metastasis." (PMID 33634028, 2020). "LAQ824, a small molecule inhibitor of histone deacetylases (HDACi), upregulated the RYBP expression in SKBr3 breast cancer cells through a miRNA27a-involving mechanism." (PMID 25344099, 2014). "Furthermore, RYBP was up‐regulated in the breast cancer cell line SK‐BR‐3 after treatment with the HDAC inhibitor LAQ824 by inducing the miR‐27a down‐regulation." (PMID 29383875, 2018).
cervical cancer (4 papers, 2009 to 2024). A primary or metastatic malignant neoplasm involving the cervix. "This study indicated a pathogenic role for the loss of RYBP in malignant progression of cervical cancer and chemoradioresistance." (PMID 29383875, 2018). "In contrast, because RYBP is located on the chromosome band 3p, an integrative genomic profile showed that RYBP was frequently down‐regulated in cervical cancer and prostate cancer due to the loss of 3p." (PMID 29383875, 2018). "Another study revealed that the genetic loss of RYBP is associated with a poor outcome after chemoradiotherapy in human cervical cancer." (PMID 25344099, 2014). "Loss of the transcriptional repressor RYBP may impair death receptor-mediated apoptosis, and the encoded protein has been shown to be down regulated in many tumor types, including cervical cancer." (PMID 19911042, 2009). "In addition, the decrease in RYBP expression in cervical cancer was positively related to poor progression‐free survival." (PMID 29383875, 2018).
Hodgkins lymphoma (4 papers, 2014 to 2024). A heterogeneous group of malignant lymphoid neoplasms of B-cell origin characterized histologically by the presence of Hodgkin and Reed-Sternberg (HRS) cells in the vast majority of cases. "In contrast, RYBP was shown to be overexpressed in cases of primary classic Hodgkin's lymphoma and adult T-cell leukemia, indicating a possible tumor type-dependent expression and function of RYBP." (PMID 25344099, 2014).
lung carcinoma (3 papers, 2018 to 2024). "RYBP inhibits the progression and metastasis of lung cancer, suppressing the epidermal growth factor receptor (EGFR) signaling and the epithelial–mesenchymal transition (EMT)." (PMID 38785968, 2024). "It has been shown that RYBP inhibits the progression and metastasis of lung cancer by suppressing EGFR signaling and EMT, and high levels of PKP1 are important to maintain a high expression of vimentin, which is a key regulator of EMT and metastasis." (PMID 38785968, 2024). "Moreover, the fact that the expression of PKP1 is high in fibroblasts and that PKP1 has been observed to be expressed in high amounts in lung cancers made the MRC-5 cell line a suitable candidate to check for the interaction between RYBP and PKP1." (PMID 38785968, 2024). "However, the molecular mechanism of RYBP in lung cancer metastasis and the relationship between RYBP and EMT is unclear." (PMID 34845670, 2022). "In addition, RYBP inhibits the progression and metastasis of lung cancer." (PMID 38785968, 2024).
melanoma (3 papers, 2015 to 2021). A malignant, usually aggressive tumor composed of atypical, neoplastic melanocytes. "In combination, evidence suggests that RYBP act as tumour suppressor gene in different solid tumours but as an oncogene in lymphoma and melanoma; however, the precise underlying mechanisms of these opposing function remain to be clarified." (PMID 29383875, 2018). "In line with the other studies, our results suggested YY1 as a transcriptional repressor of miR-9 and a promoter of melanoma growth and progression by modulating the miR-9 ~ RYBP axis." (PMID 26104682, 2015). "In the current study, RYBP, a PcG member was discovered to be a direct target of miR-9 in melanoma cells." (PMID 26104682, 2015). "Additionally, the expression of RYBP in melanoma cells was negatively regulated by miR‐9, which was suppressed by the RYBP binding protein, YY1." (PMID 29383875, 2018). "Furthermore, RYBP has also been shown to act as tumour suppressor gene in different solid tumours, but as an oncogene in lymphoma and melanoma." (PMID 29383875, 2018). "We also showed that YY1 could affect RYBP level in melanoma cells, thus forming a YY1 ~ miR-9 ~ RYBP regulatory axis." (PMID 26104682, 2015). "Collectively, our results may identify YY1 as a novel regulator of melanoma that modulates the miR-9 ~ RYBP axis to promote melanoma tumorigenesis." (PMID 26104682, 2015). "Our current study demonstrated a potential role of RYBP in melanoma tumorigenesis." (PMID 26104682, 2015). "Furthermore, to test whether the regulation of YY1 on RYBP expression is mediated by miR-9 in melanoma cells, we performed a “rescue” assay with the combination of si-YY1 and miR-9 inhibitor in WM1791C cells." (PMID 26104682, 2015). "Taken together, these results indicated that RYBP could regulate cell proliferation, migration and invasion of melanoma cells, further confirming the YY1 ~ miR-9 ~ RYBP axis in melanoma cells." (PMID 26104682, 2015). "Furthermore, RYBP and YY1 were found to co-occupy several target promoters/enhancers of YY1 to silence their expression, thereby a YY1 ~ miR-9 ~ RYBP feedback regulatory loop might be existed in melanoma cells." (PMID 26104682, 2015).
chronic rhinosinusitis (2 papers, 2012 to 2017). Chronic form of sinusitis. "It has been reported that polymorphism in the human RybP gene is associated with chronic rhinosinusitis and that RybP negatively regulates the Imd immune pathway in Drosophila." (PMID 29089430, 2017).
prostate carcinoma (2 papers, 2017 to 2018). A carcinoma that arises from epithelial cells of the prostate gland. "Furthermore, 3p14 deletions correlated positively with advanced stage, high Gleason grade and PTEN deletion in prostate cancer, implicating RYBP as a tumour suppressor gene." (PMID 29383875, 2018).
autism (1 paper, 2023). Persistent deficits in social interaction and communication and interaction as well as a markedly restricted repertoire of activity and interest as well as repetitive patterns of behavior. "RYBP, as a crucial, core component of the ncPRC1s, were mostly highlighted for its role as a repressor; however, in the past years, ncPRC1.3 and ncPRC1.5 were also identified to activate genes related to autism in the CNS." (PMID 36751888, 2023).
breast adenocarcinoma (1 paper, 2024). "In the breast adenocarcinoma, the expression of both proteins was found mostly in the cytosol, suggesting that contrary to MRC-5, the interaction of PKP1 and RYBP may occur in the cytosol." (PMID 38785968, 2024).
cardiomyopathy (1 paper, 2020). A disease of the heart muscle or myocardium proper. "Deletion of thin filament markers Tnnt2 and Tnni3 and thick filament marker Ttn in mice caused severe cardiomyopathy pinpointing the relevance that RYBP may function in the development of cardiomyopathy in humans as well." (PMID 32673370, 2020).
esophageal carcinoma (1 paper, 2024). A primary or metastatic malignant neoplasm involving the esophagus. "For example, RYBP is highly expressed in adrenocortical carcinoma (ACC), esophageal carcinoma (ESCA) and kidney chromophobe (KICH), and the high level of RYBP is positively related to shorter survival rates for patients with these tumors." (PMID 39604829, 2024).
glioma (1 paper, 2013). A benign or malignant brain and spinal cord tumor that arises from glial cells (astrocytes, oligodendrocytes, ependymal cells). "However, in a cohort which includes low grade gliomas, significant survival benefits were observed for patients with low EZH2, PHF19, CBX8 and PHC2 expression, and high CBX7, CBX6, RYBP and EZH1 expression." (PMID 24260522, 2013).
leukemia (1 paper, 2021). A malignant (clonal) hematologic disorder, involving hematopoietic stem cells and characterized by the presence of primitive or atypical myeloid or lymphoid cells in the bone marrow and the blood. "As previously observed in leukemia, USP7 depletion in SyS resulted in the partial disassembly of the ncPRC1 complex, as illustrated by the marked decrease in interactions between RING1B and RYBP in the SyS cell line HSSYII." (PMID 33361335, 2021).
Listeria infection (1 paper, 2017). "In the context of Listeria infection, OrfX decreases the level of RybP." (PMID 29089430, 2017).
nasal polyps (1 paper, 2012). "As for the subgroup analysis for the presence of nasal polyps (CRSwNP and CRSsNP) displayed significant association in CRSwNP cohorts regarding to one SNP in RYBP (rs4532099) and 5 SNPs IRAK4 (rs4252431, 6582484, rs1461567, rs4251559 and rs3794262)." (PMID 22723975, 2012). "Subgroup analysis for the presence of nasal polyps (CRSwNP and CRSsNP) displayed significant association in CRSwNP cohorts regarding to one SNP in RYBP (P = 3.24E–006, OR = 2.76)." (PMID 22723975, 2012).
neuroblastoma (1 paper, 2024). Neuroblastoma (NB) is the most common solid, extracranial childhood tumor. "RNA sequencing results showed a synergistic induction of genes associated with RA signaling (RARB, RARG), neuronal differentiation (HOXC5, PBX1), and chromatin remodeling (RYBP, JADE2), which are positively correlated with favorable prognosis in neuroblastoma." (PMID 39711563, 2024).
osteosarcoma (1 paper, 2014). A usually aggressive malignant bone-forming mesenchymal neoplasm, predominantly affecting adolescents and young adults. "In our previous study, we showed that etoposide and doxorubicin induce RYBP expression in an osteosarcoma cell line (U2OS)." (PMID 25344099, 2014).
ovarian carcinoma (1 paper, 2022). A malignant neoplasm originating from the surface ovarian epithelium. "To further support our findings that overexpressing RYBP reduces the phosphorylation of Chk2, we also repeated these experiments in ovarian cancer cell line, SKOV3." (PMID 36233063, 2022). "We, however, conclude that targeting ATM in SKOV3 is a potential important strategy in disrupting ovarian cancer proliferation, and overexpressing RYBP may offer new avenues for inhibiting ATM activity." (PMID 36233063, 2022).
Parkinson disease (1 paper, 2023). A progressive degenerative disorder of the central nervous system characterized by loss of dopamine producing neurons in the substantia nigra and the presence of Lewy bodies in the substantia nigra and locus coeruleus. "BANF1, PCGF5, WDR5, RYBP and BRD2 are related to the immune process of Parkinson’s disease and can predict the occurrence of Parkinson’s disease, which is expected to become a new target for the diagnosis and treatment of Parkinson’s disease." (PMID 36813848, 2023).
Retinal coloboma (1 paper, 2018). A notch or cleft of the retina or choroid, located vertically below the optic disc. "By constructing four RYBP mouse models, this team also showed that dysregulated RYBP expression resulted in retinal coloboma, malformed lenses, defects in anterior eye development and corneal neovascularization, indicating that RYBP plays critical roles in mouse eye development." (PMID 29383875, 2018).
uterine carcinosarcoma (1 paper, 2024). A usually aggressive malignant neoplasm arising from the uterine corpus and less often the cervix. "Conversely, RYBP is down-regulated in uterine corpus endometrial carcinoma (UCEC) and uterine carcinosarcoma (UCS), lower RYBP levels associated with shorter survival rates for patients with these malignancies." (PMID 39604829, 2024).
viral infection (1 paper, 2022). "Based on our finding that RYBP binds to KSHV lytic promoters concomitantly with H2AK119ub enrichment during the first hours of viral infection prior to PRC2 binding, we assumed that RYBP functions as a ncPRC1 factor on the KSHV genome." (PMID 36026503, 2022). "Altogether, our study revealed a novel, non-canonical role of RYBP in the regulation of KSHV gene silencing during de novo viral infection." (PMID 36026503, 2022).